SOX2 (SRY-box transcription factor 2)
Diseases named in the same sentence as SOX2 in open-access papers (continued):
Sharing a sentence is not in itself a finding about the gene and the disease.
cancer (continued). "Other reports have demonstrated that CD133 + cancer cells also express Oct4, nestin, nanog, and Sox2." (PMID 24160469, 2013). "In this study, we identified SOX2 amplification as a novel event in carcinomas of the sinonasal region." (PMID 23544055, 2013). "This possibility was verified by RNA-Seq screening of the targeted cancer genes of SOX2 by showing the up-regulated transcription of oncogenes after SOX2 gene silencing." (PMID 22615765, 2012). "The implications of these findings are discussed, especially as they relate to increases in expression of SOX2 during cancer progression." (PMID 22937156, 2012). "Overall, for both Sox2 and Oct4, only immunostaining in the nuclei of the cancer cells was thought to be positive, whereas all the precancerous tissues and benign tumor tissues showed negative staining with significant differences (p < 0.01)." (PMID 22837720, 2012). "We have reasonable ground to propose that in lung SCC, the Sox2 and Oct4 regulation network also works to co-effect the cancer stem cell differentiated and self-renewal." (PMID 22837720, 2012). "Understanding which mechanisms are used to control the expression and function of SOX2 will provide significant insight into the biological processes that are required by cancers employing SOX2 for their tumorigenicity." (PMID 22937156, 2012). "Our manuscript describes, for the first time, a novel role of SOX2 in regulating the EMT process in cancers." (PMID 22912670, 2012). "Many recent studies found that some cancers including breast carcinomas, germinomas, and pancreatic carcinomas expressed Sox2 and Oct4 simultaneously and their expression was associated with the differentiation of the tumors." (PMID 22837720, 2012). "Collectively, these results suggest that Sox2 gene has a direct role in maintaining cancer stem cell characteristics and self-renewal of SP cells from NSCLC." (PMID 23009336, 2012). "Here, we demonstrated that D121-SP cells contain cancer stem cell characteristics, that is, upregulation of the transcription factors SOX2 and Oct 4 in D121-SP cells." (PMID 21468047, 2011). "Cancer cells share pathways regulating pluripotency with embryonal stem cells, and some of the transcription factors involved, including SOX2, have indeed been identified as lineage survival oncogenes in epithelial cancers." (PMID 22190969, 2011). "So far only a small number of investigations have touched the role of SOX2 in governing cancer cell proliferation and migration capacity on the molecular level." (PMID 22070920, 2011). "The datasets of ChIP-seq, microarrays and microRNA sequencing of SOX2 response program, which, to our best knowledge, are the first datasets of SOX2 in cancers, will be useful resources for the research community." (PMID 21211035, 2011). "In fact, a meta-analysis of publicly available gene expression data suggested that at least one of the four pluripotency factors Oct3/4, SOX2, Klf4, and c-myc is overexpressed in 18 out of 40 cancer types." (PMID 20814443, 2010). "Initially, the expression of cilia within the Sox2 overexpressing tumors seemed to confound Sox2 overexpression in Scgb1a1 positive cells as a model of human cancer." (PMID 20548776, 2010). "The 16 cancer-relevant gene list that we generated, which includes genes that are likely targets of SOX2 and altered in lung SCC, is a good starting point to evaluate the molecular mechanisms downstream of SOX2." (PMID 20126410, 2010). "Selection of 16 cancer-related genes as potential mediators of the malignant phenotype of lung SCCs downstream of SOX2." (PMID 20126410, 2010). "More detailed analysis of two of the cancer related genes, sox-2 and midkine, confirmed that their expression levels increased following 5-Aza-2-deoxycytidine treatment." (PMID 20019818, 2009).
cancer (continued). "We further found that Nanog, Oct4 and Sox2 were all significantly upregulated in abnormal sperm morphology and dowregulated in malaria infection and cancer, which suggests a potential role of ES cell differentiation in these diseases." (PMID 19094235, 2008). "In KRAS-mutant cancers with G12Ci-resistant cells, SOX2, SLC7A11 and SLC40A1 are downregulated." (PMID 41516092, 2025). "When stabilized, β-catenin translocates into the nucleus, where it collaborates with the LEF/TCF transcriptional activators, leading to the binding and activation of downstream gene targets related to cancer stem cells, including c-Myc, Oct-4, Sox-2, and Nanog." (PMID 40497987, 2025). "Similarly, SOX2 aids chromatin remodelling, regulating cancer progression genes and preserving cancer stem cell characteristics, further solidifying the combined role of ATOH1 and SOX2 in MCC oncogenesis." (PMID 40589575, 2025). "Several lines of evidence have showed that SOX2 overexpression occurs in various cancer." (PMID 39994220, 2025). "Furthermore, DEHP1 and DEHP10 MCF7 cells expressed higher cancer stem cell markers, including SOX2 expression at both protein and mRNA levels and ALDH activity." (PMID 40959920, 2025). "SOX2 may play a role in inducing HLA class II expression as the group of CDX2-induced cancers with SOX2 maintenance had a slightly higher expression of these immune presenters." (PMID 40149431, 2025). "Magnetic stimulations at a moderate strength can inhibit cancer cell migration and stemness by upregulating genes associated with oxidative stress, including hyaluronan receptor (CD44), SRY-box transcription factor 2 (Sox2), and cell myc proto-oncogene protein (C-myc)." (PMID 39817348, 2025). "Collectively, these findings suggest that PP1γ may regulate YAP1 dephosphorylation and promote the expression of cancer stem cell markers SOX2 and NANOG, thereby enhancing the tumorigenic potential of ESCC cells." (PMID 40626009, 2025). "Moreover, SOX2 affects cancer cell proliferation and survival by regulating cell cycle-related genes WEE1 and cyclin-dependent kinase 1 (CDK1), making PCa cells resistant to NHRSI treatment." (PMID 40821114, 2025). "Additionally, numerous factors are involved in the cancer plasticity-mediated therapy resistance, such as transcription factors like SOX2 or ZEB1." (PMID 41190163, 2025). "Furthermore, cancer stemness markers, such as Oct4, Nanog, and Sox2, were downregulated in CAPN2 knockdown cells." (PMID 40151834, 2025). "Moreover, the co-activation of the super-enhancer-driven CCAT1 by TP63 and SOX2 has been found to promote squamous cancer progression, revealing the interplay between these TFs in cancer." (PMID 41323280, 2025). "Additionally, SOX2 is known to contribute to the development of cisplatin resistance in other cancers." (PMID 40643470, 2025). "Additionally, OCT4 cooperates with other transcription factors, particularly SOX2, to recognize and bind to specific DNA elements, forming regulatory complexes that govern gene expression programs in both pluripotent and cancer cells." (PMID 40722714, 2025). "Current cancer chemotherapy uses etoposide to induce DNA double-strand breaks for cell killing, which can cause fluctuations in stemness promoters like OCT4A, SOX-2, or NANOG in relation to senescence promoters p21Cip1, p27, or p16ink4A, and mitigate anti-cancer therapy." (PMID 40805179, 2025). "Additionally, ΔNp63α sustains cancer stem cell populations by upregulating stemness markers (e.g., SOX2, Nanog)." (PMID 40223122, 2025). "SOX2 amplification and aberrantly increased expression have been observed in various human cancers." (PMID 40227962, 2025). "Examples include overexpression of the pluripotency- and apoptosis-related POU5F1 (OCT4) (i.e., TGCT-15.6.3.P.3.0.0.2.4.2), SOX2 (i.e., LUSC-2293.6.3.P.3.62.30.1.4.3), and NANOG (i.e., TGCT-4.6.3.P.3.0.0.2.4.1) genes in various cancer types associated with stemness and poor prognosis." (PMID 41048343, 2025).
cancer (continued). "Research indicates that abnormal epigenetic alterations are common in various cancers, including PCa, and may lead to dysregulated SOX2 expression, subsequently activating oncogenes or inhibiting tumor suppressor genes." (PMID 40821114, 2025). "The upregulation of multiple lineage plasticity genes, including basal (Trp63, Krt5 and Krt14), metastasis (Snai2, Tgfb1 and L1cam), and stemness (Sox2, Mecom and Sox6) markers was induced by LKB1 loss, further supporting the enhanced cancer cell state plasticity by LKB1 loss." (PMID 39743630, 2025). "Variable SOX2 expression was noted in different types of benign and malignant neoplasms." (PMID 41176605, 2025). "Importantly, Wnt/β-catenin signaling maintains cellular stemness in part through the regulation of SOX2 expression in cancer cells." (PMID 41023726, 2025). "Moreover, a notable downregulation of SOX2, a key driver gene of cancer stemness, was observed following the knockdown of TACO1 in BCa‐CIS cells." (PMID 39656941, 2025). "Also, treatment with EC359 reduced the spheroid formation of EC cancer stem cells and reduced the levels of cancer stem cell markers SOX2, OCT4, and NANOG." (PMID 40804837, 2025). "Additionally, western blotting and qPCR showed that DDAH1 overexpression significantly upregulated Sox2, Oct4, and Nanog, which are closely related to cancer cell stemness." (PMID 40538138, 2025). "Similarly, HDAC11 promotes cancer proliferation and suppresses apoptosis, in addition to increasing Sox2 expression, maintaining cancer stem cell self-renewal, and cisplatin resistance." (PMID 40283998, 2025). "While Sox2, Oct4, and Nanog are transcription factors that are notoriously difficult to block with small molecule inhibitors, focusing on inhibiting Lin28 to prevent its binding to RNA substrates emerges as an attractive strategy for cancer therapy." (PMID 39800739, 2025). "Restoring SOX2 could theoretically reverse BE and halt progression to cancer, but transcription factors remain difficult drug targets." (PMID 40587339, 2025). "Additionally, our investigation revealed the preferential expression of CYP3A5 in cancer cells expressing the GSC markers SOX2 and CD133 via co-immunofluorescence (co-IF) staining of human GBM surgical specimens." (PMID 39754188, 2025). "Researchers observed that lncRNAs/SOX2 axes hold immense potential and could ultimately be used to improve the survival and prognosis of cancer patients." (PMID 40804837, 2025). "The differences observed in the mutation rates of WNT/APC/β-catenin pathway components in the two groups differing in SOX2 expression was in a significant degree due to the high mutation rate in MSI-high cancers, which were more prevalent in cancers with suppressed SOX2 mRNA expression." (PMID 40149431, 2025). "SOX2 (SRY-related high mobility group box 2) is a transcription factor involved in cancer stemness." (PMID 40864800, 2025). "Furthermore, SOX2 plays a significant role in enhancing the proliferation, migration, invasion, and metastasis of cancer cells." (PMID 39976818, 2025). "Other studies in other types of cancer cells have demonstrated overexpression of SOX2 promotes EMT." (PMID 40179020, 2025). "We also testedthe stem cell marker SOX2, because in a large varietyof different human cancers, it was found to be amplified or overexpressed.Enhanced SOX2 expression is considered to drive neoplastic progressionby accelerating cancer migration, invasion, and metastasis." (PMID 38739686, 2024). "The reciprocal negative regulation between Notch signaling and SOX2 described herein does not question their association with cancer stem cell features." (PMID 39478150, 2024). "Cancer stemness transcription factors such as SOX2, OCT4, and Nanog serve as markers for CSCs, which can maintain the multipotency and self-renewal of CSCs through various pathways such as promoting the EMT process, modulating the signaling pathway, and regulating the cell cycle." (PMID 38970092, 2024).
cancer (continued). "Furthermore, DRS was strongly associated with cancer stem cell markers, including CD19 (R = 0.32; p < 1.9e-13), CD44 (R = 0.21; p = 1.4e-06), and SOX2 (R = 0.29; p = 2.2e-11)." (PMID 38862242, 2024). "The majority of pharmacologic inhibitors targeting SOX2-dependent cancer growth do not target SOX2 directly but inhibit SOX2-associated signaling pathways and molecules." (PMID 38612911, 2024). "SOX2 is a stem cell transcription factor that controls self-renewal and pluripotency in cancer stem cells, and upregulation of SOX2 could be used as a marker for evaluating prognosis and treatment effectiveness for HCC." (PMID 38722372, 2024). "Kaplan-Meier plots for OS, DSS, and PFI, and ROC curves showed that SOX2 could act as a novel biomarker and predictor of prognosis in many cancer patients." (PMID 38164286, 2024). "Therefore, comprehensive analysis is required for future studies on the significance of SOX2 as a potential target for innovative cancer treatments in controlling the maintenance, progression, and stemness of LUAD." (PMID 38334608, 2024). "Thus, the role of SOX2 as an integral stemness-promoting factor in CSCs has made it an attractive target for anti-cancer therapies." (PMID 38612911, 2024). "Sox2 and Oct4 dysregulations could significantly increase in the cancer stem cell (CSC) population in some cancer cells and resistance to common treatments." (PMID 39071677, 2024). "SOX2 is a key driver of CSC-related protumor functions in many cancer types." (PMID 38612911, 2024). "Additionally, studies have substantiated the existence of cross-talks between RKIP and various cancer stem cell factors including SOX2." (PMID 38786085, 2024). "Taken together, these contradictory findings imply that studies unraveling the role of SOX2 in regulating cancer traits should be executed with meticulous consideration of its oncogenic and onco-suppressive activities as well as its specificity to different cancer types." (PMID 38334608, 2024). "Subsequent cell experiments verified that compound 77 suppressed the expression of transcription factor SOX2 (SEX determining Region Y-box 2) in cancer stem cells, and induced pluripotent stem cells (iPS) under the control of the remote enhancer targeted by LSD1." (PMID 38276629, 2024). "Loss of cancer differentiation from luminal-like to stem-like is mediated by the activation of stem cell transcription factors (scTF) such as LIN28A, NANOG, POU5F1 and SOX2." (PMID 38595814, 2024). "The downregulation of HDAC9 also decreased SOX2, a marker of cancer stemness, in AGSR cells." (PMID 38920983, 2024). "Therefore, our findings emphasize that various factors like cancer type and experimental context should be considered when unraveling the roles of stemness-regulating factors, including SOX2." (PMID 38334608, 2024). "Furthermore, the authors have found that SOX2 increases SLC7A11 to protect cancer cells from ferroptosis, and mutations in SOX2 binding sites in SLC7A11 gene sensitize cancer cells to ferroptosis." (PMID 38705513, 2024). "Moreover, for key associations with histopathologic prognostic markers, perinodal fat invasion by cancer cells was significantly predicted by the moderate/strong expression of SOX2." (PMID 38400679, 2024). "Conversely, we extended to analyze some of the cancer stem cell self-renewal marker Sox2 and Oct-4." (PMID 38957610, 2024). "Furthermore, despite the known involvement of histone deacetylases (HDACs) in cancer development and progression, the potential relationship between Sox2 and HDACs, particularly HDAC4, in CRC has received little study." (PMID 38473392, 2024).
cancer (continued). "Thus, we analyzed the effects of TOP2A inhibition by etoposide on cancer stem cell self-renewal marker Oct-4 and Sox2." (PMID 38957610, 2024). "CSPG expression was used to isolate HB Sox2+ cells for RNA-sequencing, revealing their distinguished molecular properties as typical NPSCs, which express known and newly identified genes relating to stem cells, cancer, the matrisome and cell cycle." (PMID 38251863, 2024). "Consequently, our findings highlighting its dispensable role in LUAD cells emphasize the potential for SOX2 to exhibit different functions varying according to the cancer type or context." (PMID 38334608, 2024). "While these findings challenge the conventional notion of SOX2’s indispensability in various cancer types, it is important to acknowledge and consider the potential cancer subtype-specific and context-specific role of SOX2, which can manifest differently in various types of cancers." (PMID 38334608, 2024). "Pathway analysis showed that SOX2 and its related genes play important roles in a variety of biological processes, and may activate or inhibit specific pathways across 32 different cancer types." (PMID 38164286, 2024). "Thus, SOX2 remains a dangerous transcription factor in cancer initiation and progression due to its role in maintaining aggressive, self-renewing cancer stem cells while simultaneously interacting with other oncogenic pathways." (PMID 39095874, 2024). "A recently discovered lncRNA called SOX2 overlapping transcript (SOX2OT) has a role in the growth of cancer and CSCs and may serve as a biomarker." (PMID 39170516, 2024). "Studies have also shown that SOX2 may be regulated at a transcriptional level via epigenetics, leading to SOX2 silencing in some human cancers, correlating to more aggressive biological behaviour and poorer overall prognosis." (PMID 39365497, 2024). "In cancer cells, Sox2, Oct4, and Nanog activate HERV-K 5Hs, leading to neurological illnesses." (PMID 38540701, 2024). "Additionally, SOX2 is known to regulate various functions in cancer cells, including proliferation, apoptosis, invasion, migration, ferroptosis, and drug resistance." (PMID 39867575, 2024). "In conclusion, the data unambiguously suggest that OCT4 and SOX2 cancer stem cells markers are upregulated by radiation treatment and could be playing an important role in radiation resistance." (PMID 38429272, 2024). "In addition, soft matrices in 3D models compared to rigid plastic plates enhance the CD133 mRNA levels and other cancer stem markers such as Oct4, Sox2, and Nanog in CRC cell lines." (PMID 37922108, 2024). "Interestingly, we also observed that some of the signature genes enriched in the next population on the trajectory of cancer cells (luminal cells) are upregulated in SOX2 KO cells, suggesting than SOX2 expression would need to decrease to allow the transition." (PMID 38951654, 2024). "Consequently, targeting SOX2 emerges as a potential therapeutic strategy to enhance various cancer treatments." (PMID 38334608, 2024). "In contrast, cancers with low CDX2 showed higher SOX2 expression (mean expression z-score relative to all samples = 0.42, Student’s t test p < 0.0001) and significant HNF4A suppression (mean expression z-score relative to all samples = −1.07, Student’s t test p < 0.0001)." (PMID 39768557, 2024). "Therefore, targeting SOX2 can potentially reduce cancer cell self-renewal capacity and enhance the effectiveness of cancer treatments; however, little progress has been made due to the difficulty in directly targeting transcription factors." (PMID 39463384, 2024). "In addition, hypoxia promotes CD133 expression through HIF1/2 α-induced Sox2, Oct4, and Klf4 upregulation in several cancers." (PMID 37922108, 2024). "Interestingly, combined PIK3CA and SOX2 amplification allowed us to distinguish three cancer risk subgroups, and PIK3CA and SOX2 co-amplification was found the strongest predictor by ROC analysis." (PMID 38473941, 2024).